CD4 (CD4 molecule)
Diseases named in the same sentence as CD4 in open-access papers (continued):
Sharing a sentence is not in itself a finding about the gene and the disease.
tumor (continued). "Intra-tumoral CD4+ T cell numbers were positively correlated with advanced tumor stages (p = 2.75 × 10−5), large tumor sizes (p = 0.01), positive lymph node status (p = 0.003) and HER2 expression (P = 0.03)." (PMID 25968569, 2015). "At day 28 after tumor challenge, among protected DC-vaccinated mice, CD4+T-subpopulation expressing granzyme B in C-ter-J28+DC recipient splenocytes had increased compared to that in mDC- and TnMUC1-mDC recipient splenocytes, respectively by 69% and 77%." (PMID 26405163, 2015). "In the case of tumors, MHC I molecules present tumor-associated antigens (TAA) to CD8+ cytotoxic T-cells, and MHC II molecules present TAAs to CD4+ helper T-cells, thus facilitating an anti-tumor immune response." (PMID 25690042, 2015). "The switch manifests itself as a decreased number of tumor blood vessels, increased levels of tumor-infiltrating CD4+, CD8+ and NK cells, as well as lower level of suppressor lymphocytes (Treg)." (PMID 25801067, 2015). "The frequency of CD4+ Foxp3+ regulatory T (Treg) cells is often significantly increased in the blood of tumour-bearing mice and people with cancer." (PMID 25495686, 2015). "Because chronic inflammation is one of the critical processes promoting carcinogenesis and tumor growth, Foxp3+CD4+ T cells are able to down-regulate the pro-tumorigenic inflammatory responses." (PMID 26604855, 2015). "Tumor-infiltrating Foxp3+CD4+ T cells were observed in the tumor stroma as well as tumor islets with predominant infiltration in the tumor stroma." (PMID 26604855, 2015). "These suggest that Loxoribin-treated DCs can impair Tregs' suppressive function and enhance the killing ability of CD4 /CD8 to tumor in vivo." (PMID 25593198, 2015). "In contrast, cancer patients containing low levels of tumor-infiltrating CD4+ T cells (≤16) had decreased mortality ( < 30%) and relapse ( < 20%) throughout the entire 5 year follow-up." (PMID 25968569, 2015). "The inclusion of viral proteins in these novel VLP conjugate vaccines provides foreign CD4+ T-cell help, which is especially important for tumour antigens that either fail to induce CD4+ T-cells or where such T cells have been anergized." (PMID 25692288, 2015). "Once activated, the CD4+ Th1 cells will eliminate malignant tumor cells and effectively prevent oncogenesis." (PMID 26057470, 2015). "Data analyses revealed that although the mean frequency of CD4+ T cells was lower in the tumor tissues compare to the normal tissues, the difference was not significant." (PMID 25605488, 2015). "IL2 that was produced by the CD4+ T cells alone (the value was 48.7 ± 7.3 pg/ml) significantly increased when CD4+ T cells were incubated with tumor cells and the diabody ( 333.0 ± 22.5 pg/ml)." (PMID 26444983, 2015). "On the other hand, the generation of tumor-specific cytotoxic T lymphocyte (CTL) responses is believed to depend on the help of activated CD4+ T cells, which recognize tumoral antigens presented with class II MHC molecules on antigen presenting cells." (PMID 25605488, 2015). "We next determined the effects of dacomitinib pretreatment on tumor cell recognition by HER-3-reactive CD4 T cells." (PMID 26538233, 2015). "Peripheral immune microenvironment analysis by histomorphometric and FACS assay shows that plentiful CD8+ and CD4+ T cells (CD25−Foxp3−) congregate in tumor stroma of PMSB groups." (PMID 26512920, 2015). "Next, we assessed the in vitro anti-tumor effect of TR-CD4 chTCR-transduced CD4+ T cells and compared with that of parental TR-CD4." (PMID 26447332, 2015). "PD-1/PD-L1 plays an important role in inhibiting tumor immune response by promoting CD4+ and CD8+ T cells apoptosis." (PMID 26573233, 2015). "This strategy is dependent on a robust cytotoxic CD8+ T lymphocyte (CTL) response that is supported by CD4+ T helper cells for tumor eradication." (PMID 26079374, 2015).
tumor (continued). "Taken together, these results suggest that CD4+ T cells play an essential role in the immune response to tumor growth even though the majority of cells that accumulate within the tumor exhibit a CD8+ T-em phenotype." (PMID 25901284, 2015). "These include the identification of effective tumor antigens (Ags), the induction of the HLA class II pathway for Ag processing and CD4+ T cell activation, and the ability of tumor cells to act like Ag presenting cells." (PMID 26807308, 2015). "Herein, we characterize anti-tumor effects of a unique human CD4+ helper T-cell subset that directly recognizes the cytoplasmic tumor antigen, NY-ESO-1, presented by MHC class II on cancer cells." (PMID 26447332, 2015). "In contrast, tumor-infiltrating CD4+CD8α-, CD4-CD8α- and plasmacytoid DCs contained higher lipid levels in large tumors than small tumors." (PMID 25886502, 2015). "In mice that were also administered DCs, tumor suppression was accompanied by the strongest cytotoxic T lymphocyte response of all treatment groups and by induced differentiation of CD4+ T cells, especially Th17 cells." (PMID 25826093, 2015). "Twenty-one days after tumor cell injection, T cells were harvested from the spleens and bone marrow and CD4 and CD8 T cells were enriched by immunomagnetic cell sorting." (PMID 25614821, 2015). "Better survival was found for NSCLC patents with higher Foxp3+CD4+ T cells infiltration in tumor islets, stroma or higher total Foxp3+CD4+ T cells infiltration (P < 0.05)." (PMID 26604855, 2015). "In mice, CD4+ T cells generate increased numbers of tumor-specific effector and memory CD8+ T cells." (PMID 25784913, 2015). "In contrast to the other T cell subsets, FoxP3+CD4+ Treg subpopulation had a constantly higher proportion (10-40%) in CD4+ T cell subsets from initial stage to late stage with the tumor progression." (PMID 25968569, 2015). "It is also important to consider that some other inhibitory cells infiltrate tumors, like regulatory T CD4+ cells FOXP3+ (Tregs), cancer associated fibroblasts, myeloid derived suppressor cells and tumor associated macrophages." (PMID 26487966, 2015). "At tumor site there is a slight predominance of CD4(+) cells uncorrelated with pT level, ulceration or regression." (PMID 32309563, 2015). "After migrating to tumor site, Foxp3+CD4+ T cells can inhibit the activity of cytotoxic T cells through cell-to-cell contact." (PMID 26604855, 2015). "Taken together, our data from naïve BALB/c mice and TC-1 tumor-bearing C57BL/6 mice demonstrate that GPI-0100 is able to greatly enhance TA-CIN-specific CD4+, and E7-specific CD8+ T cell responses, and L2-specific neutralizing antibody titers in serum." (PMID 25560237, 2015). "Collectively, these results highlighted the necessity of tumor-specific CD4 T cell stimulation for vaccine success." (PMID 26350591, 2015). "A future approach is to test TCR gene-engineered tumor-recognizing CD4+ T cells for their ability to potently mediate anti-tumor effects alone or in combination with MHC-I-restricted TCR-transduced T cells." (PMID 26447332, 2015). "Taking advantage of immunocompetent transgenic mouse HNSCC models, we observed a decrease in MDSCs, TAMs, and mature DCs as well as an increase in CD8+ T cells and CD4+ T cells by PD-1 blockade in micro- and macro- tumor environment." (PMID 26573233, 2015). "HER-3 reactive CD4 T cells recognized not only HLA-DR-matched tumor cell lysates but also DCs pulsed with HER-3-positive HLA-DR-unmatched tumor cell lysates." (PMID 26538233, 2015). "Their role has been documented in many other tumor models, including CD4-knockout animals, which fail to control tumor outgrowth." (PMID 25993655, 2015). "INFα increases tumor immunogenicity, activates antigen presenting cells, and stimulates both CD4+ and CD8+ T cells." (PMID 27708986, 2015). "We thus analysed the ability of effector CD4+ T cells primed in aged hosts to promote tumour-specific CD8+ T-cell responses after tumour challenge." (PMID 25850032, 2015).
tumor (continued). "There was an inverse association between a patient’s survivin reactive CD4+CD25- precursor frequency and their tumor’s survivin expression by quantitative PCR." (PMID 25992291, 2015). "Compared to wildtype littermate controls, CD4-cre x IKKβfl/fl tumor-bearing mice demonstrated a very significant reduction in specific lysis." (PMID 25648675, 2015). "As a consequence, we observed the increased recruitment of CD8+ and CD4+ T lymphocytes at the tumour lesion and especially the infiltration of mature DCs and CD8+/CD44high memory/activated T lymphocytes." (PMID 26101462, 2015). "This chemokine, having bound to the CCR4 receptor, directed migration of CD4 + CD25 + FOXP3+ lymphocytes toward neoplasm." (PMID 26077607, 2015). "In our study, we demonstrated that large numbers of CD4+ T cells that strongly react against tumor targets in a MHC-II-restricted manner can be generated by gene-engineering with TCR from tumor-recognizing CD4+ T cell clones." (PMID 26447332, 2015). "Uptake of necrotic tumor cells can induce maturation of DCs to prime antigen-specific CD4+ and CD8+ T cells and the subsequent cellular immune responses." (PMID 26403780, 2015). "On the other hand, the specific depletion of CD4+ cells had an intermediate effect and partially restored tumor growth." (PMID 26236689, 2015). "Immunization with mTrop2 VLPs led to a significant reduction in tumor growth accompanied by a broad activation and tumor infiltration of CD4 (+) and CD8 (+) T cells as well as natural killer and natural killer T cells in pancreatic cancer in mice." (PMID 26000093, 2015). "The combination of these enhanced innate immune effector activities led to increased CD8+ T cell responses and also boosted CD4+ T cell and B cell responses with notable overall anti-tumor activity." (PMID 26694473, 2015). "Anti-tumor effect of CD4+ T cells alone or in combination with CD8+ T cells was further investigated in vivo in a xenograft mouse model." (PMID 26447332, 2015). "For example, a recent study described a screening platform to detect neo-antigen-specific CD4+ T cells based on exome and RNA sequencing of the tumor followed by peptide synthesis and co-culture of neo-antigen-loaded B cells and CD4+ T cells." (PMID 25853550, 2015). "Adoptive CD4+ T cell transfer has been found to upregulate class II expression on tumor cells mediating protection from tumor progression." (PMID 25949894, 2015). "CD4+ T cells play an important role in tumor immunotherapy.It has been improved the presentation of HSP-peptide complex by CD4+ T cells is important in tumor immunosurveillance." (PMID 25961716, 2015). "Mice treated with T cells containing only CD8+ or CD4+ cells demonstrated tumor response and survival to 40 days, suggesting that both T cell subtypes play a role in antitumor activity." (PMID 26090481, 2015). "As we all know, CD4+Th cells are essential to the immune response of anti-tumor and Th1 cells, a predominant Th cell subtype characterized by IFN-γ and TNF-α secretion." (PMID 26378021, 2015). "CD4+CD25+ cells have been shown to dampen local anti-tumor responses and prevent sterilizing immunity against certain chronic infectious agents." (PMID 26564056, 2015). "For example, CD4+CD25highFoxP3+ Treg are frequently increased in tumor bearing hosts and contribute to tumor-related immune suppression, since they can be induced by tumor-deriving factors." (PMID 25961061, 2015). "CD4+CD25+Foxp3+ Tregs were considered as a crucial factor that suppress the anti-tumor function of Effector CD8+ T cells." (PMID 26451607, 2015). "After vaccination, peptide-specific CD4+ T cells became detectable and a subset of these vaccine-induced CD4+ T cells showed tumor-recognizing ability." (PMID 26447332, 2015). "In cancer patients, spontaneous CD4 T cell responses against tumor antigens have been detected in several studies." (PMID 26350591, 2015).
tumor (continued). "The combination therapy highly increased the numbers of tumor-infiltrating CD4+ and CD8+ lymphocytes as well as IFN-γ production." (PMID 26500646, 2015). "Depleting CD4+T cells significantly enhanced tumor growth and shortened survival (P < 0.01, vs. isotype control)." (PMID 26447613, 2015). "In previous studies, the correlation of the number of CD4+CD25+Foxp3+ Tregs in TDLNs with tumor stage and survival was contradictory." (PMID 25990075, 2015). "After capturing the tumor antigens, these mature and transport the antigen to lymph nodes where they present the tumor antigen to naive T lymphocyte cells (CD4+ and CD8+ T lymphocytes)." (PMID 26054860, 2015). "Fewer CD4-cre x IKKβfl/fl than wildtype splenocytes secreted IFN-γ upon restimulation with irradiated MC57-SIY tumor cells." (PMID 25648675, 2015). "These cells, also named tumor infiltrating lymphocytes (TILs), are composed of different kind of lymphocytes, including CD4+ and CD8+ T cells, Tregs, B cells, NK cells and NKT cells." (PMID 26305693, 2015). "Upon direct recognition of cancer cells, tumor-recognizing CD4+ T cells (TR-CD4) potently induced IFN-γ-dependent growth arrest in cancer cells." (PMID 26447332, 2015). "In this study, CD4+ T cells also mediated significant anti-tumor effector functions in this ovarian CSC vaccination." (PMID 26673159, 2015). "Within the tumour environment, we observed that the percentage of all cell types examined (with the exception of CD4+ cells (T cells)) were significantly greater in pEEVGmCSF-b7.1-treated tumours when compared with untreated tumours." (PMID 25373914, 2015). "CD4+ T-cell content among the TILs in RCC has been shown in several studies to correlate with unfavorable tumor characteristics and patient outcome." (PMID 26317902, 2015). "Although both adoptively transferred CD4 and CD8 cells were required for tumor regression, CD4 cells were more effective." (PMID 26090481, 2015). "It has been reported that CD4+ T cells have a distinct role in tumor immunosurveillance based on cytokine production and/or cytotoxicity at tumor sites." (PMID 25961716, 2015). "After 168 hours the percentage of CSPG4 positive tumor cells killed by the CD4+ and CD8+ cell fraction rose up to 97%, as only 3% viable tumor cells were left." (PMID 26469402, 2015). "CD4+ T cells are critical for priming of tumor-specific CD8+ T cells and for the seconary expansion and memory of CD8+ T cells as well." (PMID 25968569, 2015). "The presented antigens activate the CD4+ T cell which in turn recruit TAA-specific CD8+ T cells that lead to further killing of tumor cells." (PMID 26464579, 2015). "Recent studies have shown that CD4+CD25+ regulatory T cells are of great importance to the maintenance of tumor-induced immune tolerance by inhibiting the activation and proliferation of autoreactive T cells." (PMID 26564056, 2015). "The results indicated a significant increase in both the proportion and absolute numbers of CD4+CD25+ T-cells in the peri-tumor region." (PMID 25654227, 2015). "For example, IFN-γ production from CD4 T cells augments MHC class I expression on tumor followed by CD8 T cells-mediated tumor killing." (PMID 26538233, 2015). "The Th2 CD4+ T cells, Th17 CD4+ T cells, Foxp3+CD4+ regulatory T (Treg) cells can play a pro or anti-tumoral role, depending on the tumor microenvironment." (PMID 25741340, 2015). "A significant increased infiltration of both CD8+ and CD4+ T cells into the tumor was observed after fractionated RT when combined with DTIC and HT." (PMID 25973681, 2015). "CD4+CD25+ regulatory T cell depletion is indicated to sensitize an established tumor to immunotherapy." (PMID 26564056, 2015).
tumor (continued). "The role of CD4+ T cells in anti-tumor immunity has recently been extensively studied in both pre-clinial animal models and and clinical cancer patients." (PMID 25968569, 2015). "CD4+ T cell dysfunction has been readily described in tumor bearing mouse models and cancer patients and represents a major challenge to the successful application of immunotherapy for cancer." (PMID 25875653, 2015). "Another important player in the tumor immune evasion process is the CD4+CD25+FOXP3+ T-regulatory cells (Tregs)." (PMID 26464579, 2015). "Similar reductions in the percent of CD8α+CD4- DCs were seen in the dLN of large tumor-bearing mice and in the spleens of small and large tumor-bearing mice." (PMID 25886502, 2015). "In this study, the expression of CD4+ T cells were significantly increased in advanced tumor stage, large tumor size and positive lymph nodes metastasis, compared to that in early group." (PMID 26587366, 2015). "CD8α+CD4- DCs play a key role in anti-tumor immunity due to their ability to cross-present tumor antigen to CD8+ T cells." (PMID 25886502, 2015). "Tumor-infiltrating CD4+ and CD8+ T cells play important role in the immune response to cancer cells in NSCLC." (PMID 26604855, 2015). "The balance between effector immune cells such as CD8+ cytotoxic T cells and CD4+ “helper” T cells) and suppressor immune cells such as Tregs and MDSCs is a critical determinant of effective anti-tumor activity." (PMID 26573233, 2015). "VISTA blockade also alters the suppressive character of the tumor microenvironment, reducing MDSCs, increasing DC activation and enhancing the proliferation and the effector function of tumor-infiltrating CD4 and CD8 T cells." (PMID 26347741, 2015). "Metastasis of SLB-1 cells, as judged by human CD4 staining of a subcutaneous tumor and of the lung, was also striking in the lung." (PMID 26597716, 2015). "In this context, its direct actions on tumor cells, either growth stimulatory or inhibitory, and the modulation of tumor specific cytotoxic CD4-, CD8-, LAK- and NK-cells are of interest and should be further studied." (PMID 26406983, 2015). "It has been shown that PD-1 expression on CD4+ effector T cells and the presence of CD4+Foxp3+ Tregs suppress anti-tumor responses." (PMID 25851535, 2015). "Solitomab acts by engaging resting polyclonal CD8+ and CD4+ T cells for highly potent redirected lysis of target tumor cells that express EpCAM." (PMID 26474755, 2015). "Whereas in E0771-bearing mice, only CD4+IL17+ and CD4+Foxp3+ subsets had significant increases in tumor draining lymph nodes." (PMID 25968569, 2015). "Clinical studies have additionally shown an increase in circulating tumor-specific CD4+ and CD8+ T cells in hepatocellular carcinoma patients (HCC) at 4 weeks post-RFA treatment." (PMID 26599402, 2015). "Because of their ability to directly recognize tumor targets, the TR-CD4 in this study is unique and distinct from conventional CD4+ T cells that require antigen cross-presentation by APCs for activation." (PMID 26447332, 2015). "CD4+CD25+T cell (Treg) is an immune regulating subtype which is regarded to play immunosuppressive role in tumor microenvironment." (PMID 26161392, 2015). "This strong anti-tumor response was paralleled by an increased tumor infiltration rate of CD8+ T cells while numbers of tumor-infiltrating CD4+ T cells were unaltered." (PMID 25815272, 2015). "FoxP3+ regulatory CD4+ T-cells (Tregs) are another subset of functionally immunosuppressive hematopoietic cells that infiltrate the HNSCC tumor microenvironment and suppress effector T-cells via a number of mechanisms." (PMID 26690220, 2015). "We expected that the efficiency of vaccination (anti-tumor/anti-metastatic response) would depend on the CD4+/CD8+ ratio and correlate with switching between Th1 and Th2 responses." (PMID 26325576, 2015).